C3 (complement C3)
Diseases named in the same sentence as C3 in open-access papers (continued):
Sharing a sentence is not in itself a finding about the gene and the disease.
myocarditis (5 papers, 2013 to 2025). Myocarditis is a condition that is characterized by inflammation of the heart muscle (myocardium). "On the other hand, STAT3 contributes to immune-mediated myocarditis due to IL-6-induced complement component C3 production in the liver, as well as the differentiation of Th17 cells, which play a role in initiation and development of myocarditis." (PMID 30619368, 2018). "Further, we demonstrate that STAT3 is sufficient when constitutively active for triggering the onset of immune-mediated myocarditis, involving enhanced complement C3 production and IL-6 signalling amplification in the liver." (PMID 23460527, 2013). "Further, we demonstrate that STAT3 is sufficient when constitutively active for triggering the onset of auto-immune myocarditis, involving enhanced complement C3 production and IL-6 signalling amplification in the liver." (PMID 23460527, 2013). "Patients with acute myocarditis displayed elevated circulating IL-6 and C Reactive Protein levels, which correlated with significantly higher circulating C3, compared to healthy controls or to samples from DCM or chronic myocarditis." (PMID 23460527, 2013). "This appears to be relevant to disease pathogenesis in humans, since acute myocarditis patients display significantly elevated circulating IL-6 and C3 levels and activated heart STAT3." (PMID 23460527, 2013). "Thus, aberrant IL-6/STAT3-mediated induction of liver acute phase response genes including C3, which occurs as a consequence of pre-existing inflammatory conditions, might represent an important factor determining the degree of myocarditis and its clinical outcome." (PMID 23460527, 2013). "This did not affect the onset or severity of myocarditis in those Stat3C/C mice already showing high C3 or anti-α-myosin antibodies at the time of treatment, in agreement with the predicted role of C3 in the inductive phase." (PMID 23460527, 2013). "Notably, the pattern of IgG and C3 deposition was consistent between IHD and myocarditis HF tissue." (PMID 32850816, 2020).
polyarthritis (5 papers, 2012 to 2026). "Her SLE had been diagnosed a year earlier, presenting with polyarthritis, positive antinuclear and anti-dsDNA antibodies, and low levels of C3 and C4." (PMID 42005993, 2026). "Prior studies have shown that the C3 cleavage product C3a is elevated in synovial fluid of RRV polyarthritis patients." (PMID 22457620, 2012). "All exhibited mucocutaneous involvement, DLE rash, polyarthritis, coarse-speckled ANA, anti-RNP antibodies and normal C3/C4 levels." (PMID 40556690, 2025).
proliferative diabetic retinopathy (5 papers, 2011 to 2025). Advanced retinopathy due to diabetes mellitus characterized by the formation of new vessels in the retina. "On the other hand, proteomics analysis of vitreous and AH shows proteins that participate in a complementary system: clusterin, complement C3, and C4-A, which are factors that can serve as biomarkers for proliferative diabetic retinopathy (PDR)." (PMID 34575451, 2021). "The same study also showed increased mRNA expression of C3 and factor B in the retina from other diabetic patients with proliferative diabetic retinopathy (PDR)." (PMID 22046295, 2011). "Activation of the complement pathway has been demonstrated by increased protein expression of several factors such as C3, C4b, C9 and factor B in the vitreous of diabetic patients with proliferative diabetic retinopathy." (PMID 22046295, 2011).
prostate carcinoma (5 papers, 2020 to 2025). A carcinoma that arises from epithelial cells of the prostate gland. "Supporting the link between complement activation, chronic inflammation, and prostate tumorigenesis, a large plethora of observational studies detected increased level of C3 fragments in the serum of prostate cancer patients, particularly in the elderly." (PMID 34572075, 2021). "Interestingly, three components of the complement system, namely C3, C1R, and CFB, also showed a significant upregulation after interaction with the metastatic cell line MDA-MB231 and two of them (C3 and C1R) could be validated in the prostate cancer model." (PMID 31963450, 2020).
sarcoma (5 papers, 2020 to 2024). A usually aggressive malignant neoplasm of the soft tissue or bone. "In patients with sarcomas, C3 deficiency-associated genetic signatures predicted better clinical outcomes supporting protumorigenic function of C3." (PMID 35860237, 2022). "Furthermore, genetic deficiency of PTX3 is associated with increased deposition of C3 on sarcoma cells, and administration of the exogenous protein abrogates this effect via FH-dependent mechanisms." (PMID 33324220, 2020). "As a result, the significantly positive correlation between C3 and macrophage enrichment was observed in our pan-sarcoma dataset and in histological subtypes LMS, SS, WDLPS, and AS." (PMID 38360860, 2024). "A recently published study demonstrated that C3 is activated through the lectin pathway during sarcoma progression." (PMID 35725556, 2022).
sickle cell disease (5 papers, 2018 to 2025). Sickle cell anemias are chronic hemolytic diseases that may induce three types of acute accidents: severe anemia, severe bacterial infections, and ischemic vasoocclusive accidents (VOA) caused by sickle-shaped red blood cells obstructing small blood vessels and capillaries. "Regarding rs117793540 C3, in a study of 81 adult Sickle Cell Disease (SCD) patients conducted by our group, 25 rare variants were detected, while rare variant rs117793540 was identified and characterized as pathogenic in the C3 gene." (PMID 40724958, 2025). "Here, the case report n°4, showing MPGN with C3 deposits following a PVB19 infection in a patient with sickle cell disease, is particularly original and illustrates this possible link between PVB19 and CAP activation." (PMID 32646497, 2020). "The heme scavenger protein hemopexin has been efficient in preventing hemolysis-mediated C3 deposition in kidneys in a mouse model of intravascular hemolysis and on endothelial cells in vitro, as well as in models of stasis in sickle cell disease or other hemolytic conditions." (PMID 30619356, 2018).
staphylococcal infection (5 papers, 2010 to 2024). An infection caused by Staphylococcus. "The Sbi protein interferes with innate immune recognition by binding multiple host proteins including the complement factors H and C3 as well as IgG (the Sbi protein traps human IgGs) and β2-glycoprotein I, suggesting that Sbi has a role during staphylococcal infections." (PMID 20532214, 2010).
streptococcal infection (5 papers, 2016 to 2024). Any of the several infectious disorders caused by members of streptococcus, a genus of gram positive bacteria belonging to the family Streptococcaceae. "APSGN was defined by the clinical presentation of at least two clinical signs of acute nephritis, and low serum complement 3 (C3) level or evidence of a recent streptococcal infection." (PMID 38170231, 2024). "Renal biopsy in previous case reports of PRS secondary to streptococcal infection showed enlarged glomeruli, neutrophilic infiltrates, IgG and C3 deposition along the mesangium—findings consistent with APSGN." (PMID 27231692, 2016).
urinary tract infection (5 papers, 2020 to 2024). "Concomitantly we sought to evaluate whether C3a/C3 is involved in urinary tract infections (UTI) often associated with such disease conditions." (PMID 34767613, 2021). "For example, C3 levels in women with recurrent urinary tract infections have been shown to be lower than in healthy women." (PMID 34858876, 2021). "It seems that with the improvement of urinary tract infection symptoms, complement C3 increased, but hematuria and proteinuria did not change significantly." (PMID 39969315, 2024).
ZIKV infection (5 papers, 2019 to 2023). "(a) ZIKV infects neurons in the hippocampus and frontal cortex (b) ZIKV infection causes upregulation of complement proteins (C1q and C3), which is associated with microglial activation and pro-inflammatory response." (PMID 34408631, 2021). "BDV induced local C1q mRNA expression in the hippocampus and cortex and ZIKV infection enhanced expression of C1q and C3, associated with microglial activation and hippocampal synaptic damage and memory impairment in a murine infection model using ZIKV intracerebroventricular infusion." (PMID 34408631, 2021). "We also detected C3 induction in mouse sera after ZIKV infection, which indicated systemic C3 induction." (PMID 37191498, 2023). "Diacerein, an inhibitor of IL-1β production, and an IL-1R antagonist effectively reduced the ZIKV-mediated C3 induction in a dose-dependent manner, thereby suggesting the involvement of IL-1β in the induction of C3 gene expression by ZIKV infection." (PMID 37191498, 2023). "To evaluate the functional consequences of C3 induction and complement activation by ZIKV infection, we determined the C5a levels in the brain." (PMID 37191498, 2023). "ZIKV infection upregulated C3 expression through IL-1β-mediated signaling, possibly disrupting the balance of the complement system, which can mediate myelin phagocytosis by macrophages." (PMID 37191498, 2023). "Taken together, our findings indicate that the induction of C3 and complement activation by ZIKV infection is mediated by the IL-1β signaling pathway." (PMID 37191498, 2023). "C1q and C3 upregulation has also been described during ZIKV infection of the adult mouse brain and proposed to influence synapse formation." (PMID 37022660, 2023). "Analysis of all cell clusters further indicated that other complement components, such as C1ra, C1s1, and C3, were also upregulated in monocytes, macrophages, or fibroblast-like clusters after ZIKV infection." (PMID 37120617, 2023). "To validate the role of C/EBP-β in IL-1β-mediated induction of C3 expression by ZIKV infection in THP-1 cells, we infected cells with ZIKV at 5 MOI and analyzed the activation of P38, Erk1/2, and C/EBP-β using Western blotting." (PMID 37191498, 2023). "TNF-α upregulation, microgliosis and upregulation of complement system proteins, C1q and C3, are induced by ZIKV infection." (PMID 31488835, 2019). "Interestingly, results show induction of components of the complement system that were common to both DENV and ZIKV in the brain such as CfB and C3, but C2 and C4a—components of the classical and lectin pathways, were only induced by ZIKV infection." (PMID 37022660, 2023). "The increase in C3 levels by ZIKV infection is mediated by IL-1β signaling." (PMID 37191498, 2023). "We thus measured the expression of C1q and C3 in the brains of mice following ZIKV infection." (PMID 31488835, 2019). "ZIKV infection of THP-1 cells induced pyroptosis, increased IL-1β release, and consequently increased C3 expression." (PMID 37191498, 2023). "Altogether, results suggest that ZIKV infection leads to elevated brain levels of TNF-α, microglial activation and increased expression of C1q and C3, culminating with synapse damage and memory impairment in adult mice." (PMID 31488835, 2019). "Therefore, we demonstrated that ZIKV infection in THP-1 cells promotes C/EBP-β expression through IL-1β induction, eventually resulting in increased C3 levels." (PMID 37191498, 2023). "Indeed, ZIKV infection induced C/EBP-β expression and its activation through phosphorylation, which was conducted by activated p38 but not Erk1/2, resulted in the elevation of C3 expression." (PMID 37191498, 2023).
adenoma (4 papers, 2016 to 2023). A neoplasm arising from the epithelium. "The analysis of colonic adenomatous nodes revealed low expression of all the explored acute colitis-associated key genes: the expression levels of C3, Tyrobp, Mmp3, Mmp9, and Timp1 in adenoma tissue were 26.3, 3.4, 20.8, 11.9, and 27.7 times lower than those in the samples with acute colitis." (PMID 36901742, 2023). "H&E staining showed that adenoma formation was accompanied by diffuse immune cells infiltration in the colons of WT, C3-deficient, and C5ar2-deficient mice, while more mucosa-associated lymphoid tissues suspected as tumors were observed in C5- and C5ar1-deficient mouse colons." (PMID 32754267, 2020). "C1M, C3M, and collagen 3 (pro-C3) identifies CRC subjects with respect to controls, and C1M and pro-C3 are significantly higher in serum from CRC versus adenoma patients, rendering them potential markers in making an early differential diagnosis." (PMID 30678058, 2019).
angioedema (4 papers, 2011 to 2023). Swelling involving the deep dermis, subcutaneous, or submucosal tissues, representing localized edema. "Because angioneurotic edema was a possibility, the complement components C3 and C4 and C1 esterase inhibitor (C1-INH) were tested." (PMID 36523733, 2022). "It is not recommended to measure complement C3 and CH50 levels, as they are near normal in angioedema." (PMID 21320328, 2011).
bacterial pneumonia (4 papers, 2018 to 2025). Acute infection of the lung parenchyma caused by bacteria (e.g., Streptococcus pneumoniae, Haemophilus influenzae, Chlamydia pneumoniae, Mycoplasma pneumoniae, and Legionella pneumophila). "Deletion of C3 from epithelial cells in the lung has demonstrated how epithelial cell–derived C3 mitigates bacterial pneumonia–induced acute lung injury." (PMID 41031895, 2025). "Further analysis indicated that most patients with bacterial pneumonia (46.7%) had elevated C3 levels, with C4 levels remaining within the normal range." (PMID 38585537, 2023). "A consistent finding with other infectious models such as bacterial pneumonia has been that mice lacking C3 (and factor B) exhibit an increased susceptibility and more pronounced acute lung injury than WT counterparts." (PMID 39628481, 2024).
choroidal neovascularization (4 papers, 2015 to 2021). An eye disorder described by the growth of new blood vessels that originate from the choroid through a break in the Bruch membrane into the sub–retinal pigment epithelium (sub-RPE) or subretinal space. "The complement pathways, via the activation of C3, can upregulate the expression of cytokines and their receptors and the recruitment of inflammatory leukocytes, both of which play an important role in the development of choroidal neovascularization (CNV) in exudative AMD." (PMID 26507897, 2015).
chronic hepatitis C (4 papers, 2009 to 2016). "Specific protein fragments of matrix metalloprotease degraded type I, III, IV and VI collagen (C1M, C3M, C4M, C6M) and type III and IV collagen formation (Pro-C3 and P4NP7S) were assessed in plasma from 403 chronic hepatitis C patients by specific ELISAs." (PMID 26406331, 2015).
colon adenocarcinoma (4 papers, 2016 to 2025). "Studies have shown that C3 is also an immune-related core differential protein in colon adenocarcinoma (COAD) and is negatively correlated with the overall survival of COAD patients." (PMID 36741376, 2022).
coronary atherosclerosis (4 papers, 2020 to 2022). Atherosclerosis of the coronary vasculature. "Proteome profiling of serum revealed a change in the content of kininogen, hemopexin, transthyretin, retinol-binding protein, and proteins of the complement system (C9, and C3) in coronary atherosclerosis." (PMID 33033454, 2020). "Proteomic studies of the blood of patients with coronary atherosclerosis showed an increase in the content of components of the complement system C3 (chain B), C4, C9 and a decrease in the level of the complement component C3 (chain C)." (PMID 34948066, 2021).
frontotemporal dementia (4 papers, 2019 to 2025). Frontotemporal dementia (FTD) comprises a group of neurodegenerative disorders, characterized by progressive changes in behavior, executive dysfunction and language impairment, as a result of degeneration of the medial prefrontal and frontoinsular cortices. "More recently, in a mouse model of frontotemporal dementia caused by progranulin deficiency, there is a striking elevation in C1q expression in the microglia, resulting in concomitant tagging of dysfunctional synapses by C3 and phagocytosis." (PMID 31906973, 2020). "In mouse models of Alzheimer’s Disease and frontotemporal dementia (FTD), C3 and C1q associate with synapses, and microglia recognize and engulf these synapses in a CR3 (complement receptor 3)-dependent manner." (PMID 38106879, 2023). "In mouse models of Alzheimer’s disease (AD) and frontotemporal dementia (FTD), elevated levels of complement factors cause early synaptic loss which can be rescued by inhibition or deletion of C1q, C3 or CR3." (PMID 30758770, 2019).
kidney cancer (4 papers, 2022 to 2025). Primary or metastatic malignant neoplasm involving the kidney. "Both clusters contain a substantial proportion of C3, which was most common in kidney cancer and had a moderate level of tumor proliferation and elevated lymphocyte amount, reaching an immunologic control of cancer." (PMID 37305457, 2023).
leishmaniasis (4 papers, 2009 to 2024). Infectious disease that is transmitted through the bite of hematophagous female phlebotomine sand flies. "During leishmaniasis, leishmanolysin-like proteins are involved in inactivation of complement C3, inhibition of host cell interactions, perturbations in host cell signaling and degradation of the extracellular matrix." (PMID 19885392, 2009).
leprosy (4 papers, 2011 to 2024). Leprosy is a chronic infectious disease affecting primarily the skin and peripheral nervous system. "In lepromatous leprosy lesions, all these genes exhibit high levels of expression, which is consistent with the M2 macrophage phenotype, characterized by the high production of C3 (an element of the complement system)." (PMID 39308868, 2024). "The patient described in this case report had RPGN and biopsy findings suggestive of PIGN with C3 and IgA detected on immunofluorescence and kidney injury secondary to recent infection by Staphylococcus, a well-documented manifestation of renal impairment in patients with Hansen's disease." (PMID 30160772, 2018).
liver failure (4 papers, 2014 to 2024). A liver disease characterized by the liver losing or has lost all of its function. "In a mouse 70% partial hepatectomy model, C3- and C5-deficient mice succumb to liver failure, a phenotype rescued by the reconstitution of effector molecules C3a and C5a." (PMID 36341433, 2022). "C3 deficiency or C3a antagonists improved survival in alcoholic liver disease or in liver failure models." (PMID 27144164, 2016). "An animal liver failure model recently showed activation of complement as evidenced by the hepatic deposition of C3 and C5b-9." (PMID 27144164, 2016). "Other important disease-relevant processes such as liver failure (LCAT, LDHA), complement activation (C3) and tissue damage (MB, H2AC17, ACTB) were also represented by the ML features." (PMID 39681038, 2024).
malnutrition (4 papers, 2012 to 2024). Inadequate nutrition resulting from poor diet, malabsorption, or abnormal nutrient distribution. "Our research finds that underweight is an independent risk factor for kidney disease progression in IgAN, which might be associated with malnutrition status and decreased C3 levels." (PMID 27611091, 2016). "However, increased consumption is also supported by one study showing high levels of C3d, a by-product after activation of C3, in malnourished children, most pronounced in oedematous malnutrition." (PMID 25153531, 2014). "All these patients exhibited decreased C3 levels, which might reflect severe comorbid conditions such as malnutrition." (PMID 22792353, 2012). "On one hand, the total complement and C3 may be at a critical level in patients with malnutrition." (PMID 27611091, 2016). "Two studies found C3 to correlate with albumin, and with one exception, C3 levels were lower in children with oedematous than non-oedematous malnutrition." (PMID 25153531, 2014).